BAX (BCL2 associated X, apoptosis regulator)
Diseases named in the same sentence as BAX in open-access papers (continued):
Sharing a sentence is not in itself a finding about the gene and the disease.
testicular cancer (2 papers, 2020 to 2025). A primary or metastatic malignant neoplasm that affects the testis.
varicocele (2 papers, 2020 to 2024). A condition characterized by the dilated tortuous veins of the spermatic cord with a marked left-sided predominance. "In varicocele patients, the apoptosis-related protein B-cell lymphoma 2 (BCL2) was downregulated, while BCL2-associated X protein (BAX) was upregulated." (PMID 39685846, 2024). "Animals subjected to varicocele showed an increased mRNA expression of the pro-apoptotic BAX compared to sham and also to contralateral testes." (PMID 32466161, 2020). "The treatment with lycopene significantly reduced BAX mRNA expression in both operated and contralateral testes, compared to the testes of varicocele rats." (PMID 32466161, 2020). "Varicocele-induced damage markedly increased and decreased the pro-apoptotic BAX and the anti-apoptotic Bcl-2 gene expression, respectively; this strongly suggests that the apoptotic process was stimulated in varicocele rats." (PMID 32466161, 2020).
abdominal aortic aneurysm (1 paper, 2023). Enlargement and ballooning of the vessel that supplies arterial blood to the abdomen, pelvis and legs.
acromegaly (1 paper, 2024). Acromegaly is an acquired disorder related to excessive production of growth hormone (GH) and characterized by progressive somatic disfigurement (mainly involving the face and extremities) and systemic manifestations. "BAX expression was significantly lower in all patients: acromegaly (median RQ = 0.31; P <0.001), Cushing’s disease (median RQ = 0.21; P = 0.007) and NF (median RQ = 0.41; P =0.005)." (PMID 39449743, 2024).
acute respiratory distress syndrome (1 paper, 2023). Progressive and life-threatening pulmonary distress in the absence of an underlying pulmonary condition, usually following major trauma or surgery. "Additionally, an increased ratio of BCL-2 to the proapoptotic protein BCL2-associated X (BAX) has been measured in fibroblasts isolated from patients with nonresolving fibroproliferative acute respiratory distress syndrome (ARDS) compared with resolving ARDS." (PMID 36752201, 2023).
alcoholic liver diseases (1 paper, 2022). A disorder caused by damage to the liver parenchyma due to alcohol consumption. "Therefore, EPPH strongly modulates Bcl-2 and BAX involved in apoptosis, thereby exhibiting cytochrome P450 (CYP)-inhibitory effects in alcoholic liver disease cells." (PMID 36101395, 2022).
amelanotic melanoma (1 paper, 2019). A melanoma characterized by the complete absence of melanin pigment in the melanoma cells. "Within this context, other authors have demonstrated that molecules as Diazaphenothiaznes exert an antiproliferative activity in MCF7 cells and C32 human amelanotic melanoma, by regulating BAX and BCL2 gene expression." (PMID 30744145, 2019).
angiosarcoma (1 paper, 2022). A malignant tumor arising from the endothelial cells of the blood vessels. "In the present study, NECTIN4 knockdown downregulated BCL-2 and upregulated BAX in angiosarcoma cell lines and induced apoptosis." (PMID 35256687, 2022). "Because NECTIN4 knockdown also decreased Akt and Src phosphorylation, we speculate that these signals are involved in regulation of BCL-2 and/or BAX by NECTIN4 and affects tumor progression of angiosarcoma." (PMID 35256687, 2022).
anxiety disorder (1 paper, 2025). A category of psychiatric disorders which are characterized by anxious feelings or fear often accompanied by physical symptoms associated with anxiety. "BAX and BCL-2 are critical proteins involved in the regulation of apoptosis, and their roles in anxiety disorders have garnered increasing attention in recent years." (PMID 40509387, 2025).
bronchopulmonary dysplasia (1 paper, 2025). Bronchopulmonary dysplasia is a chronic respiratory disease that results from complications related to lung injury during the treatment of infant acute respiratory distress syndrome in low-birth-weight premature infants or from abnormal lung development in older infants. "Identifying pro-apoptotic proteins that BCL2 counteracts, such as BAX, BAK, and/or BOK, and unraveling their upstream regulators will provide further insights into AMF apoptosis mechanisms, which may be disrupted during impaired alveologenesis in bronchopulmonary dysplasia." (PMID 40492191, 2025).
cervix adenocarcinoma (1 paper, 2024). "To address potential interferences from the HCT116 cellular background affecting the behavior of the BCL2 TMD mutants, we investigated the homo- and hetero-oligomerization of BCL2 TMD with BAX TMD in the HeLa cervix adenocarcinoma cell line." (PMID 38670940, 2024).
chlamydial infection (1 paper, 2022). "Indeed, in cultures of chlamydia-infected mouse embryonic fibroblasts (MEFs) deficient in proapoptotic BAX, the spread of chlamydial infection to formerly uninfected cells appeared to have been impeded." (PMID 36219107, 2022).
chondrosarcoma (1 paper, 2017). A malignant cartilaginous matrix-producing mesenchymal neoplasm arising from the bone and soft tissue. "Phosphorylated PI3K/AKT can promote cell growth and decrease apoptosis via increased Bcl-2/BAX ratio in human chondrosarcoma (CS)." (PMID 28887597, 2017).
dermatitis (1 paper, 2019). An inflammatory process affecting the skin. "In this prospective cohort study, we found that symptoms of dermatitis radiation, pain, pruritus and fatigue were associated with the expression level of some genes of the DNA-damage response pathway (FDXR, SESN1, XPC, ZMAT3, ATM, BCL2/BAX, and CDKN1A)." (PMID 31632918, 2019).
Desminopathy (1 paper, 2021). "Desmin-positive protein aggregates correlate with high levels of ATF2, voltage-dependent anion-selective channel protein 1 (VDAC1), and BCL2 Associated X (BAX) in muscle fibers of desminopathy patients." (PMID 34272480, 2021).
diabetic cardiomyopathy (1 paper, 2024). Diabetic cardiomyopathy is a disorder of the heart muscle in people with diabetes. "In another study on diabetic cardiomyopathy, it was reported that NKILA was highly expressed in high sugar-induced AC16 cells, and apoptosis protein markers such as BAX, CASP3, and CASP9 were increased, while anti-apoptosis protein BCL-2 was inhibited." (PMID 39184397, 2024).
diabetic retinopathy (1 paper, 2019). "In addition, analysis of TUNEL and apoptosis-related indicators (cleaved caspase 3 and BAX/Bcl-2 ratios) further confirmed that pancreatic kallikrein could improve apoptosis in diabetic retinopathy." (PMID 30838453, 2019).
E. coli infection (1 paper, 2021). "E. coli infection increased BAX and Caspase-3 p17 expression levels and BAX to Bcl-2 ratio and decreased Bcl-2 expression level; LGR-1 pretreatment reversed these phenomena." (PMID 34594329, 2021).
Ehrlich tumor (1 paper, 2021). "The treatment with the Fr-BuVt (200 mg/kg, 14 days) decreased the solid Ehrlich tumor volume and weight besides increased the expression of the pro-apoptotic proteins caspase-3 and BAX, but also decreased the expression of the proteins involved in proliferation NFκB, mTOR and ERK." (PMID 33413302, 2021).
Fulminant hepatitis (1 paper, 2025). Acute hepatitis complicated by acute liver failure with hepatic encephalopathy occurring less than 8 weeks after the onset of jaundice. "They analyzed how after liver resection surgery, there is a progressive increase in the levels of PUMA, BAX and BCL-XL, which is related to an increase in apoptosis, in Kupffer cells induction and in neutrophils infiltration, as well as a higher number of fulminant hepatitis and mortality." (PMID 41440983, 2025).
hemolytic-uremic syndrome (1 paper, 2025). Acute kidney injury associated with microangiopathic hemolytic anemia and thrombocytopenia. "Escherichia coli O157:H7 expressing Shiga toxin Stx2 binds globotriaosylceramide (Gb3) receptors on renal glomerular endothelia, triggering BAX/BAK-mediated mitochondrial apoptosis and subsequent hemolytic uremic syndrome (HUS)." (PMID 41008233, 2025).
hemophilia B (1 paper, 2018). Hemophilia B is a form of hemophilia characterized by spontaneous or prolonged hemorrhages due to factor IX deficiency. "The FIX Padua ELISA data, therefore, provided unambiguous evidence that expression of FIX Padua was elicited in the patients treated with BAX 335, and they support implementation of the assay in FIX Padua-based hemophilia B gene therapy trials." (PMID 30003118, 2018). "The description of hyper-functional factor IX (FIX) Padua triggered the development of BAX 335, an AAV8-based hemophilia B gene therapy vector designed to compensate for low FIX protein expression levels by expressing the FIX Padua variant, thereby reducing the exposure to viral vector." (PMID 30003118, 2018).
Hernia (1 paper, 2020). "Although these genes have not yet been associated with hernias, the BAX gene, from the BCL2 family, has already been considered a candidate for the occurrence of scrotal hernia in pigs." (PMID 31973088, 2020).
histiocytic lymphoma (1 paper, 2023). "Compared to B lymphocyte cell line SU-DHL-4 and histiocytic lymphoma cell line U937, BAX was low expressed in the NKTL cell lines." (PMID 37160920, 2023).
hyperlipidemia (1 paper, 2021). "In addition, inflammatory molecules and apoptosis-related proteins, such as IL-6, TNF-α, and BAX, were abnormally elevated in patients with hyperlipidemia." (PMID 34307504, 2021).
hyperuricemia (1 paper, 2023). An abnormally high level of uric acid. "Furthermore, as downstream molecules of Bcl‐2 in the apoptosis pathway, we observed elevated proapoptotic BAX and cleaved caspase‐3 levels in the hyperuricemia model." (PMID 37502610, 2023).
iris disease (1 paper, 2005). "Thus, BAX-mediated processes are not necessary for the progression of the iris disease." (PMID 16103918, 2005).
ischemic cardiomyopathy (1 paper, 2025). Ischemic cardiomyopathy is a cardiomyopathy in which a weakness in the muscle of the heart due to inadequate oxygen delivery to the myocardium with coronary artery disease being the most common cause. "In summary, during the development of ischemic cardiomyopathy, the activation of BAK/BAX by multiple pathways plays an essential role in cell apoptosis and necroptosis, ultimately resulting in poor prognosis and increased mortality in patients with IR." (PMID 41514922, 2025). "During the development of ischemic cardiomyopathy, the activation of BAK/BAX by multiple pathways leads to cell apoptosis and necroptosis, ultimately resulting in poor prognosis and increased mortality in patients with MI/IR." (PMID 41514922, 2025).
kidney stone (1 paper, 2023). "Our findings suggest that BSHS may inhibit kidney stone formation mainly by regulating estrogen and estrogen receptor levels, inhibiting oxidative stress processes, reversing apoptosis, and decreasing CaOx crystals deposition through E2/ESR1/ESR2, NRF2/HO-1, and BCL2/BAX signaling pathways." (PMID 36864834, 2023).
Leber congenital amaurosis (1 paper, 2022). Leber congenital amaurosis (LCA) is a retinal dystrophy defined by blindness and responses to electrophysiological stimulation (Ganzfeld electroretinogram (ERG)) below threshold, associated with severe visual impairment within the first year of life. "Increased BAX activation was also found in the Rpe65−/− mouse for Leber congenital amaurosis; however, inhibition of BAX only slowed rod, but not cone, degeneration." (PMID 35054919, 2022).
leiomyoma (1 paper, 2012). A well-circumscribed benign smooth muscle neoplasm characterized by the presence of spindle cells with cigar-shaped nuclei, interlacing fascicles, and a whorled pattern. "As to the BAX expression of the single tumors a higher sensitivity of the leiomyomas compared to their matching myometrium was noted except for two cases (683 and 687) where with 10 μM the expression in the myometrium slightly exceeded that of the leiomyoma." (PMID 22233735, 2012). "As a rule for both genes i.e. p21 and BAX leiomyoma tissue turned out to be more sensitive than myometrial tissue." (PMID 22233735, 2012). "For the same cases used before and one additional case (one leiomyoma plus matching myometrium) samples of myometrial tissue have been treated with 3 μM and 10 μM nutlin-3 for 72 h to analyze and compare the expression of p21, and BAX with that of the matching leiomyomas." (PMID 22233735, 2012). "Interestingly, we were able to show that antagonizing MDM2 induces the activity of genes associated with senescence (p21) as well as those with apoptosis (BAX) in leiomyoma cells in vitro." (PMID 22233735, 2012).
leukodystrophies (1 paper, 2021). "In this context, our rescue studies show that blocking BAK or BAX can enhance oligodendrocyte survival, suggesting that treatments that inhibit the intrinsic apoptotic pathway in the postnatal brain may provide an avenue for reducing the impact of diverse leukodystrophies." (PMID 34873168, 2021).
leukopenia (1 paper, 2024). "Through molecular docking analysis, it was discovered that QJSB has a significant impact on the expression of apoptotic proteins BAX, BCL2, CASPASE3, and CYTC in mice with leukopenia." (PMID 39295929, 2024).
Li-Fraumeni syndrome (1 paper, 2024). "Mutations in BAX have been suggested to confer cancer predisposition, leading to a phenotype resembling Li-Fraumeni syndrome." (PMID 38892746, 2024).
liposarcoma (1 paper, 2017). A usually painless malignant tumor that arises from adipose tissue. "The drug increased apoptosis as shown by upregulation of cleaved caspase 3, cleaved PARP and BAX, as well as annexin V positive staining of liposarcoma cells." (PMID 27893412, 2017).
Lynch syndrome (1 paper, 2018). An autosomal dominant hereditary neoplastic syndrome characterized by the development of colorectal carcinoma and a high risk of developing endometrial carcinoma, gastric carcinoma, ovarian carcinoma, renal pelvis carcinoma, and small intestinal carcinoma. "Recent studies have shown that virtually all (99%) CRCs developing in Lynch syndrome patients display MSI-H; the most mutated genes exhibiting microsatellite repeats are ACVR2A, TGFBR2, EGFR, BPMR2, E2F4, MSH3, BAX and TCF7L2." (PMID 29652830, 2018). "In the MSI pathway observed in Lynch syndrome, CRC formation is driven by the acquisition of mutations at the level of the coding sequences of genes, such as growth factor receptors (TGFBR2 and IGF2R), genes involved in apoptosis (BAX) and DNA repair (MSH3 and MSH6)." (PMID 29652830, 2018).
male infertility (1 paper, 2024). The inability of the male to effect fertilization of an ovum after a specified period of unprotected intercourse. "Visualization of this complex environmental health dataset illuminates candidate genes (BAX, BCL2, and SOD2) and phenotypes (male gonad development, apoptosis, and spermatogenesis) connecting the chemicals to male infertility, and thus may represent critical intermediate molecular mechanisms." (PMID 39104826, 2024).
meningioma (1 paper, 2015). A generally slow growing tumor attached to the dura mater. "NDRG4 gene knockdown resulted in decreased expression of Bcl-2 and BcL-xL, translocation of activated BAX into the mitochondria, cytochrome c release and enhanced cleaved caspase expression in meningioma cells." (PMID 26053091, 2015).
metastatic colorectal cancer (1 paper, 2007).
mood disorder (1 paper, 2018). A cognitive disorder a disturbance in which the person's mood is hypothesized to be the main underlying feature. "In encephalic regions closely associated with mood disorders, namely the PFC, NAc and Hip, altered duration of lighting led to upregulated HINT1, accompanied by increased BAX and decreased BCL-2." (PMID 29937721, 2018).
nasopharyngeal tumors (1 paper, 2013). "As demonstrated by Cox univariate regression analysis, NPC patients with BAX mRNA-positive nasopharyngeal tumors were at lower risk of death (HR = 0.27, 95% CI = 0.12–0.59, P = 0.001), compared to NPC patients whose biopsies were BAX-negative." (PMID 23777485, 2013). "Undoubtedly, future studies are needed to elucidate the functional role of BAX in nasopharyngeal tumors." (PMID 23777485, 2013). "M0 patients with BAX-positive malignant nasopharyngeal tumors had more favorable DFS and OS rates than did M0 patients with BAX-negative malignancies (P < 0.001 and P = 0.009, respectively)." (PMID 23777485, 2013). "Cox proportional hazard regression analysis confirmed that BAX is a significant independent prognostic factor in NPC, as patients with BAX-positive nasopharyngeal tumors were at a reduced risk of relapse and death, independently of their gender, age, tumor histology, tumor extent, and nodal status." (PMID 23777485, 2013). "BAX positivity was more frequently observed in nasopharyngeal tumors of small tumor extent (T1 and T2) rather than in more extended NPC (T3 or T4; P = 0.014)." (PMID 23777485, 2013).
Nephropathy (1 paper, 2020). A nonspecific term referring to disease or damage of the kidneys. "Since cisplatin-induced nephropathy is characterized by mitochondrial damage of tubular cells and upregulated expression of BCL2-associated X protein (BAX), which is one of the major proteins inducing mitochondrial apoptosis by permeabilizing its membrane, we evaluated the expression of BAX mRNA." (PMID 32528023, 2020).
nephrotoxicity (1 paper, 2025). Toxicity that causes injury to the kidney or damages its function. "In contrast, the kidneys of rats in the Genta-induced nephrotoxicity group displayed marked cytoplasmic reactivity (+++) for BAX in proximal and distal tubules and moderate cytoplasmic reactivity (++) in collecting tubules." (PMID 39235475, 2025).
neuroendocrine lung tumors (1 paper, 2022). "The ratio of BAX and BCL2 expression becomes an important marker of survival in patients with neuroendocrine lung tumors." (PMID 36354566, 2022).
neuronal tumor (1 paper, 2014). Neuronal brain tumors are an uncommon group of central nervous system tumors that arise from cells with neuronal differentiation. "In neuronal tumor cells, high expression of mitochondrial survivin inhibited BAX relocalization into mitochondria and subsequent release of cytochrome c and ROS production." (PMID 25140197, 2014).
odontogenic tumors (1 paper, 2025). "When compared to odontogenic tumors, OKC/S has similar BAX expression to AMc, UAs, and AOTs, suggesting that it plays an essential role in maintaining cell populations in odontogenic lesions with aggressive and non-aggressive local growth." (PMID 40818142, 2025).